ATM (ATM serine/threonine kinase)
Diseases named in the same sentence as ATM in open-access papers (continued):
Sharing a sentence is not in itself a finding about the gene and the disease.
tumor (continued). "No efficacy was seen in the ATM-proficient model, whereas in the ATM-KO tumours we observed a 61% TGI after 3 weeks of treatment." (PMID 32741974, 2020). "The knockdown of DNA polymerase θ did not affect tumor cell growth, and a combination of ATM inhibition impaired cell growth." (PMID 33182492, 2020). "Its lack in the frontal recurrence in the absence of chromosomal aberrations at the ATM 11q22.3 locus suggests that this tumor evolved from a subpopulation of the initial frontotemporal tumor distinct from the one that gave rise to the rest of the foci." (PMID 32014051, 2020). "Our results suggest that ATM status should be carefully assessed in tumours from patients with PDAC and that the distinction between ATM-low and ATM-null could be crucial in maximising the success of trials using ATM expression as a predictive biomarker." (PMID 32741974, 2020). "ATM status should be carefully assessed in tumours from patients with PDAC, since distinction between ATM-low and ATM-null could be critical in maximising the success of clinical trials using ATM expression as a predictive biomarker." (PMID 32741974, 2020). "Almost half of recurrent IDHWT tumours (43%; 3/7) harboured at least one potentially actionable variation in the genes EGFR (14%; 1/7), PTEN (14%; 1/7), BRCA1 (14%; 1/7), BRCA2 (14%; 1/7), and ATM (14%; 1/7)." (PMID 32082376, 2019). "Molecular testing determined that his t-NEPC tumor (but not his original adenocarcinoma) harbored complete copy number loss of BRCA2, as well as copy number loss of another HR gene - ataxia telangiectasia, mutated (ATM)." (PMID 31565603, 2019). "Inhibition of ATM reversed EMT and inhibited cell invasion and tumor metastasis." (PMID 30961670, 2019). "We did not examine the effect of the combination of the ATR inhibitor and the ATM inhibitor, but adding both VE822 and KU60019 may more strongly enhance the anti-tumor effect of irradiation." (PMID 31805725, 2019). "In ER− tumours that received no chemotherapy, MYC overexpressed tumours with low ATM protein levels had the worst survival." (PMID 30746633, 2019). "NEPC and Enzalutamide-resistant CRPC are known to be more metastatic and ATM has been shown to promote tumor migration and invasion through its non-DNA repair functions." (PMID 30657058, 2019). "Interestingly, Genufu subtype (ER+/HER-2−/low proliferation) and PAM50.Luminal A subtype were common in tumours with low MYC mRNA and high ATM mRNA expressions all adjusted p values ≤ 0.01)." (PMID 30746633, 2019). "In particular, the subclonal trajectory that characterizes the primary regions is initiated by a stopgain SNV in the DNA damage repair gene ATM, whereas the subclonal metastatic expansion seems to originate by a stopgain SNV in GNAQ, a gene reponsible for diffusion in many tumour types." (PMID 31023236, 2019).
tumor (continued). "The remaining five mutation positive Group 1 tumours lacking a BRAF mutation possessed an FGFR1, NF1, ARID1B, HIST1H3B, and ATM mutations, respectively." (PMID 29058119, 2018). "On the contrary, TRF1, TRF2 and ATM showed lower expression in tumor, statistically, however, the difference was not significant." (PMID 29870526, 2018). "Six genes were found to be altered in two tumours: MYO1A, DNAH11, SH2D5, ATM, MUC4 and ROS1." (PMID 29665859, 2018). "Regarding tumor site, telomere length, ATR, ATM and Chk1 were shown to be altered." (PMID 29870526, 2018). "Both, ATM and CHEK2, were negatively associated with triple‐negative breast cancer (TNBC) and estrogen receptor (ER)‐negative tumor phenotypes." (PMID 29522266, 2018). "No OncoScan data were available for tumour T0001, but the CNV profile obtained from the WGS data showed LOH at 11q21-q24.2 (containing ATM) and also loss/LOH at 13q13.3-q32.3, 17p13.3 and 22q12.3-q13.31." (PMID 29665859, 2018). "The reduction of ATM expression in NPC was further substantiated in the IHC analysis in an independent cohort of 35 histologically normal nasopharyngeal epithelia (NP) and 46 primary NPC tumor cases (p < 0.0001)." (PMID 29230817, 2018). "Median ATM expression in our NSCLC cohort was 4490 (red line) and fell in the upper end of the normal lung epithelium 95% C.I., indicating moderate overexpression in tumour tissue." (PMID 28418844, 2017). "However, in response to IR, some tumor cells activate DSBs repair and pro-survival pathways such as EGFR/ATM/ATR/BRCA1/Chk1 and PI3K/Akt or RAS/Raf/ERK1/2, rendering them radio-resistant." (PMID 28423495, 2017). "Expression of dominant negative AKT weakly and variably enhanced cell death in tumor cells transfected to knock down the expression of ATM or AMPK." (PMID 27903966, 2017). "In previous studies, ATM and ATG4C were reported to have a tumor-suppressive role." (PMID 28423511, 2017). "The median ATM expression index in our NSCLC cohort was 0.851 (red line) and fell in the lower end of the normal lung epithelium ATM-EI 95% C.I., indicating modest under expression in tumour tissue." (PMID 28418844, 2017). "Skeletal muscle that had been infiltrated by tumour cells was mainly negative for ATM/ATR but some staining was seen for DNA-PKcs (data not shown)." (PMID 27527858, 2016). "The 90% negative tumor nuclei cutoff for ATM low/negative used here was chosen to be consistent with that previously established in the literature." (PMID 27259260, 2016). "ATM and MRE11 protein expression levels in the TC were tested in a forward and reverse binary logistic regression analysis using a data set of immunohistochemical scoring derived from 257 tumor samples and 255 normal tissues." (PMID 27930716, 2016). "Multivariable analysis indicated that the combination of high ATM and low Ki67 is prognostic of improved survival, independent of tumor size, grade, and lymph node status (p = 0.02)." (PMID 27741524, 2016). "Similarly, ATM and MRE11 protein expression levels in the TP (tumor, n = 258; normal, n = 255) were also tested, and the model gave an average ROC-AUC value of 0.837." (PMID 27930716, 2016).
tumor (continued). "As expected, the rates of liquid plasma-induced cell death in the coculture system (which mimics tumor heterogeneity) were comparable to the death rates under the single culture conditions for ATM and BRCA1 positive and negative cells." (PMID 27364630, 2016). "miR-101 targets the 3′UTRs of DNA-PK and ataxia telangiectasia mutated (ATM) mRNAs to influence both the non-homologous end joining (NHEJ) and homologous recombination (HR) DNA damage repair processes and to sensitize tumor cells to radiation." (PMID 27225532, 2016). "Moreover, we identified an inverse correlation between ATM protein expression and World Health Organization (WHO) tumour grading." (PMID 26220524, 2015). "Only one tumor had both MYCN amplification and ATM deletion." (PMID 26053094, 2015). "As a next step, we performed experiments aiming at demonstrating more directly that the tumor promoting effect of ATM silencing is not mediated by MYCN." (PMID 26053094, 2015). "In the current study we therefore explored if patient stratification could be achieved based on XRCC1, ATM, DNA-PKcs and ATR expression statuses in tumours." (PMID 26674120, 2014). "The aim of this study was to describe the morphological characteristics and the DNA methylation status of the CDKN2A,CDH1, ATM, FHIT and RAR- genes in the central and peripheral part of the tumor and the surgical margin and evaluate their prognostic significance." (PMID 24782031, 2014). "ATM, ATR, DNA-PKcs and XRCC1 protein expressions were investigated in a Cox multivariate model that was also adjusted for FIGO stage, grade, and residual tumour burden after surgery, chemotherapy and CA-125 response." (PMID 26674120, 2014). "Such selectivity for SATB1 activity suggests that reduced ATM level serves as a molecular determinant for SATB1 tumor-inducing activity in non-malignant cells." (PMID 23251624, 2012). "As expected for a direct substrate of ATM,6, 10, 13 a positive signal for p-53BP1 was more frequently found in tumours with high p-ATM in comparison to negative/low p-ATM [odds ratio (OR) = 2.206; 95% CI = 1.383–3.519; p = 0.001]." (PMID 22323184, 2012). "Increased mRNA levels of ATM and DNA-PKcs, but not of Ku80, were detected in tumor tissues when compared with adjacent normal tissues." (PMID 22348039, 2012). "The anti-tumor effect of PARP inhibitor in ATM-negative, metastatic NETs should be studied in the context of clinical trials." (PMID 22485171, 2012). "Indeed, while ATM activity constitutes a barrier to malignant transformation, full activation of ATR and CHK1 is essential for tumor maintenance, providing important opportunities for therapeutic intervention." (PMID 22373487, 2012). "Interestingly, our results showed that several molecules involved in DNA damage/repair (ATM, CHK2 and Ku80) were increased in tumor tissues." (PMID 22348039, 2012). "We showed that ATM-negativity was not significantly correlated with clinicopathologic parameters such as tumor site, histology grade, sex, and age." (PMID 22485171, 2012).
tumor (continued). "The data show that, as was the case with the tumor cell lines A549 and TK6, growth of lymphocytes in the presence of 5mM metformin distinctly reduced both the level of constitutive expression of γH2AX as well as of ATM-S1981P." (PMID 22067284, 2011). "Selected CRC target genes involved in apoptosis (BAX), tumor growth (TGFβRII), WNT pathway (AXIN2, TCF4, WISP3), DNA repair (ATM, ATR, BLM, BRCA1, BRCA2, DNAPKcs, MBD4, MRE11, MSH3, MSH6, RAD50, XRCC2) and PI3-kinase signaling (PTEN) were analyzed for mutations in MSI-positive HGG samples." (PMID 21637783, 2011). "Unlike normal cells, tumor cells often show significant activation of ATM and ATM dependent check point pathways under non-stressed conditions." (PMID 19545411, 2009). "It is therefore tempting to speculate that the activation status of ATM and CHK2 may significantly interfere with the radiosensitivity and/or chemosensitivity of tumour cells." (PMID 17940507, 2007). "Concerning the potential predictive value of ATM, no impact on tumour regression or overall survival was detectable." (PMID 17940507, 2007). "While these data provide important mechanistic insights into the interaction between ATM inhibition and Topo-II induced DNA damage, they may not fully reflect the complexity of tumor microenvironments or pharmacokinetics in vivo." (PMID 41557625, 2026). "Therapeutically, exploiting this dependency using DDR-targeted agents (ATM, ATR, DNA-PKcs, or PARP inhibitors) is a promising strategy to overcome resistance, as it can tip the balance between the extensive DNA damage induced by SBRT and the tumor’s capacity to repair it." (PMID 40725389, 2025). "Indeed, ATM-3507 synergizes with low concentrations of the microtubule-disrupting drug vincristine, a component of R-CHOP, to block mitosis and induce apoptosis in various tumor cell lines." (PMID 41268543, 2025). "When defects occur in the ATM/ATR signaling pathway, both ATM‐mediated HRR and NHEJ repair pathways fail to activate properly, resulting in decreased DSBs repair efficiency, accumulation of intracellular DNA damage, and ultimately increased tumor cell sensitivity to chemotherapeutic agents." (PMID 41473689, 2025). "In senescent cells, DNA damage triggers ATM/ATR kinase activation, which phosphorylates the IKK complex to degrade IκBα, enabling nuclear translocation of the p65/p50 heterodimer—a prerequisite for SASP factor transcription (IL-6, IL-8, MMP9) that fosters a tumor-promoting inflammatory niche." (PMID 40510156, 2025). "In preclinical models, ATM and ATR inhibitors together with IR created a more favorable anti-tumor immune microenvironment (e.g. increased cytotoxic T-cells, decreased Tregs), increased T-cell receptor diversity, generated immunologic memory and combined with immunotherapies improved tumor control." (PMID 40181161, 2025). "To test this hypothesis, we first constructed ATM knockdown stable cell lines in four TNBC cell lines, MDA-MB-231, HCC1937, SUM159 and BT549, and found that the expression of MHC-I (HLA-A + HLA-B) on the surface of tumor cells was increased by flow cytometry." (PMID 40825766, 2025).
tumor (continued). "Among these, the natural compound Shikonin specifically induces proteasome‐dependent degradation of ATM‐ATR Interacting Protein (ATRIP), inhibiting the activation of upstream regulatory factors in the DDR signaling pathway, thereby enhancing the sensitivity of tumor cells to chemotherapeutic agents." (PMID 41473689, 2025). "In a semiquantitative analysis, the immunohistochemical stainings of ATM, DNA-PKcs and Ku80 were scored as either negative, weak, moderate or strong depending on the staining intensity and the respective portion of the tumor cells stained, following a well-established algorithm." (PMID 39478631, 2024). "Finally, ATMi pre-treatment resulted in the attenuation of the CX-5461 response in both cell lines, suggesting that ATM-dependent signaling potentiates the tumor-killing mechanism of CX-5461 irrespective of the Top2α status." (PMID 39062087, 2024). "Of note, while the initial DNA lesions sensed by ATM or ATR are diverse, downstream signaling cascades are to some extent overlapping and, hence, the integration of ATM and ATR as well as the cell cycle and tumor cell signaling status will influence the net outcome of the DDR." (PMID 37041372, 2023). "These suggest that the non-canonical roles of ATM play critical functions in tumor suppression." (PMID 37190230, 2023). "Compared with the negative-control group, low ATM expression stimulated tumor-cell proliferation." (PMID 37674118, 2023). "Similarly, patients with negative ATM tumor expression did not benefit from the addition of olaparib to paclitaxel." (PMID 36975505, 2023). "Further exploration of ATM inhibitors confirmed that ATM inhibition may upregulate Gal-9 expression through the cGAS-STING-IFN-β signaling pathway, an important mechanism mediating tumor immune escape." (PMID 37305685, 2023). "Pharmacologic inhibition of ATM, via KU-60019 and AZD1390 at non-toxic doses, restored and even synergized with IR in PTEN-deficient human and murine NSCLC cells as well in a multicellular organotypic ex vivo tumor model." (PMID 35477555, 2022). "This can be explained by the frequent identification of several alterations that point towards identical treatment recommendations (e.g., BRCA mutation, ATM underexpression, FANCI, FANCA deletion for PARP inhibitors in the same patient) but were not always all named by both tumor boards." (PMID 36274133, 2022). "This tumor bottleneck can be exploited, as wild type nor tumor cells relied on active ATM for cell proliferation, at least ex vivo, and tolerated ATM inhibition via KU-60019 or AZD 1390, while in combination with ionizing radiation PTENmutant cells, human and murine, succumbed to therapy." (PMID 35477555, 2022). "Despite the high germline conversion rate, the European Society of Medical Oncology Precision Medicine Working Group did not recommend germline-focused tumor analysis for ATM because no consensus had been reached on management strategies for the risk within families." (PMID 35008949, 2022). "Furthermore, blockage of ATM, MAPK, and mTOR signaling pathways with inhibitors also prevented citrate‐induced overexpression of ACAT1/2 and cPLA2α for LD formation in MCF7 and HCT116 tumor cells." (PMID 34747157, 2022). "In addition, conditions that activate ATM and ATR as part of DDR may also participate in regulating the innate immune system and alert it to potentially ‘dangerous’ tumour cells." (PMID 36106115, 2022).